ATM (ATM serine/threonine kinase)
Diseases named in the same sentence as ATM in open-access papers (continued):
Sharing a sentence is not in itself a finding about the gene and the disease.
esophageal cancer (12 papers, 2010 to 2025). A primary or metastatic malignant neoplasm involving the esophagus. "In addition, the expression of p-ATM in esophageal cancer was significantly associated with TNM stage (P < 0.001), T classification (P = 0.008) and relapse (P = 0.045)." (PMID 36260180, 2022). "Analysis of HMGB1 and p‐ATM expression was performed on biopsies from patients with esophageal cancer." (PMID 40740483, 2025). "Another research evaluated how HMGB1 affects the sensitivity of esophageal cancer cells to radiation by controlling the PI3K/AKT/ATM pathway." (PMID 40740483, 2025). "In this study, we aim to detect the internal mechanism of HMGB1 affecting the radio-sensitivity of esophageal cancer cells through PI3K/Akt/ATM pathway." (PMID 36260180, 2022). "The combination of HMGB1 and p-ATM expression can better predict the prognosis of patients with esophageal cancer after chemo-radiotherapy." (PMID 36260180, 2022). "We observed that downregulation of HMGB1 protein resulted in changes in p-AKT and p-ATM expression of esophageal cancer cells." (PMID 36260180, 2022). "At the same time, patients with high expression of p-ATM showed late T stage, and prone to relapse which indicate that p-ATM is closely related to the local progression of esophageal cancer." (PMID 36260180, 2022). "We observed the expression of HMGB1 and p-ATM in biopsies of esophageal cancer patients with immunohistochemical staining." (PMID 36260180, 2022). "Their findings also suggested that the ATM gene should be further evaluated as a biomarker for the early detection of esophageal cancer in patients." (PMID 24888564, 2014). "In conclusion, we found a combination of HMGB1 and p-ATM may predict the prognosis of esophageal cancer patients with chemo-radiotherapy." (PMID 36260180, 2022). "Down-regulation of HMGB1 may promote the radio-sensitivity of esophageal cancer cells through regulating PI3K/Akt/ATM pathway." (PMID 36260180, 2022). "Esophageal cancer patients with high expression of HMGB1 and p-ATM have a poor prognosis after chemo-radiotherapy." (PMID 36260180, 2022). "Specifically, VUS in the ATM gene (ENST00000278616:p.S1584R, VAF 49.8%) was detected in a patient with esophageal cancer and predicted to be somatic by ISOWN." (PMID 35033101, 2022). "This study highlights HMGB1 as a key regulator of esophageal cancer radioresistance, acting via the PI3K/AKT/ATM axis, and suggests that its inhibition could improve radiotherapy outcomes through enhanced cell death and impaired invasion." (PMID 40740483, 2025).
esophageal squamous cell carcinoma (12 papers, 2015 to 2025). Esophageal squamous cell carcinoma (ESCC) is a type of esophageal carcinoma (EC) that can affect any part of the esophagus, but is usually located in the upper or middle third. "A Western blot was performed to verify that silencing RNF168 activated the expression of ATM in esophageal squamous cell carcinoma cells." (PMID 33493132, 2021). "SNHG20 promotes tumorigenesis through the ATM-JAK-PD-L1 pathway in esophageal squamous cell carcinoma (ESCC)." (PMID 32042268, 2020). "In esophageal squamous cell cancer, lncRNA FAM201A was reported to upregulate radioresistance via miR-101/ATM axis." (PMID 35600868, 2022).
brain cancer (11 papers, 2008 to 2025). A primary or metastatic malignant neoplasm affecting the brain. "The pro-tumorigenic role of ATM in brain cancer is somewhat unexpected, since ATM deletion accelerated tumorigenesis in an in vivo mouse model of human GBM." (PMID 29348882, 2017). "In the context of brain cancer related radiosensitizer research, chemoradiation investigations were prominent in the 20th century, while articles from the 21st century highlight nanoparticles, ATM inhibitors, mTOR inhibitors and inhibition of PARP." (PMID 40667051, 2025). "In addition, the activated p-ATM-related DNA repair pathway and anti-apoptotic genes in the CD133+ subset could be warranted as possible targets to improve the therapy for the treatment of advanced malignant brain tumors." (PMID 18509505, 2008).
diffuse large B-cell lymphoma (11 papers, 2004 to 2025). "In diffuse large B cell lymphoma patients, ATM mutations were the most frequently represented, affecting nearly 15% of patients, followed by POLQ which was mutated in 10.6%." (PMID 33214570, 2020). "ATM mutations have been reported in diffuse large B-cell lymphoma (DLBCL) and follicular lymphoma (FL)." (PMID 14735203, 2004). "We show that ATM deficiency in diffuse large B-cell lymphoma (DLBCL) significantly induce mitochondrial deacetylase sirtuin-3 (SIRT3) activity, disrupted mitochondrial structure, decreased mitochondrial respiration, and compromised TCA flux compared with DLBCL cells expressing wild type (WT)-ATM." (PMID 33273545, 2020).
Huntington disease (11 papers, 2010 to 2024). Huntington disease (HD) is a rare neurodegenerative disorder of the central nervous system characterized by unwanted choreatic movements, behavioral and psychiatric disturbances and dementia. "Dysregulation of ATM signalling has also been addressed to Huntington’s disease (HD), a genetic neurodegenerative disorder caused by a CAG-repeat expansion in the first exon of the HTT gene encoding the huntingtin protein." (PMID 32858941, 2020). "Another neurological disorder presenting the importance of the ATM/Chk2 pathway in its pathology is Huntington’s disease (HD)." (PMID 39062967, 2024). "It has also been suggested that the persistent DDR and the inappropriate activation of the ATM signaling pathway may play a role in the development of fragile X syndrome and Huntington’s disease." (PMID 39062967, 2024). "Considering that the activation of ATM, an important regulator of the DNA damage response, induces cell apoptosis, and inhibition of ATM reduces the severity of Huntington’s disease in both cellular and animal models, we focused on ATM in the following studies." (PMID 37737187, 2023). "Since a key function of the MRN complex is to recruit and activate ATM at double-strand breaks, and given that Huntington’s disease-pathology is reduced by targeting ATM, we asked whether inhibiting ATM directly would also be neuroprotective to RGC." (PMID 32954257, 2019). "Potential drugs or interventions for the treatment of neurodegenerative diseases (NDs), including Parkinson’s disease (PD), Huntington’s disease (HD), and Alzheimer’s disease (AD), are classified by mechanisms, including epigenetic misregulation, ATM, and neuroinflammation." (PMID 26712747, 2015). "If a similar loop were operating in cells expressing expanded polyglutamine proteins one might expect to find ROS-mediated DNA damage leading to activation of ATM and phosphorylation of histone H2AX, as has indeed been documented in cells from Huntington's disease and SCA-2 patients." (PMID 20885783, 2010). "Caffeine, a nonspecific inhibitor of ATM and other phosphatidylinositol 3-kinase family members, protects against etoposide-induced DNA damage and cell death in neurons in vitro, and genetic reduction of ATM gene dosage is neuroprotective in mouse models of Huntington’s disease." (PMID 36103534, 2022). "Similarly caffeine, a non-specific inhibitor of ATM, is neuroprotective against etoposide-induced DNA damage to neurons in vitro and reducing ATM gene dosage is neuroprotective in a mouse model of Huntington’s disease." (PMID 32954257, 2019).
Infertility (11 papers, 2012 to 2026). "In mammals, knockout ATR mutation results in embryonic lethality, while an ATM mutation results in pleiotrobic defects (e.g., growth defects, neurologic dysfunction, and infertility)." (PMID 24833228, 2013). "ATM-deficient mice were infertile, and ovaries from mutant females were devoid of primordial and maturing follicles and oocytes, indicating that an ATM deficiency not only promotes apoptosis in granulosa cells but also in oocytes, as ATM plays an important role in DNA repair." (PMID 22737216, 2012). "ATM−/− mice show pleiotropic defects (growth retardation, infertility, immune defect and high incidence of T cell lymphomas), and ATR−/− mice show embryonic lethality." (PMID 24833228, 2013). "For example, ATM knockout mice are viable, but display growth retardation, infertility, defects in T lymphocyte maturation, and extreme sensitivity to γ-irradiation." (PMID 22448250, 2012). "These fish could not fertilize wild-type (WT) oocytes, while those that were outcrossed indicated the infertility of ATM−/− fish." (PMID 35203601, 2022). "However, ATM plays critical roles in germline development as A-T patients present with gonadal dysgenesis and both male and female mice lacking ATM are infertile due to defects in meiotic progression." (PMID 23532176, 2013).
ischemic heart disease (11 papers, 2016 to 2024). "ATM variants have been associated with a predisposition for developing ischemic heart disease." (PMID 35872888, 2022). "Siblings and parents of A-T patients carrying heterozygous ATM mutation can present increased health risks and decreased life expectancy due to ischemic heart disease and increased susceptibility to develop cancer, especially breast and digestive tract cancers." (PMID 33142696, 2020). "Furthermore, variation in the ATM gene has been associated with coronary artery disease." (PMID 26606753, 2016). "Earlier studies have demonstrated that this SNP affects the expression of ATM mRNA through differentially binding to AP-2a, an important factor that regulates transcription of the ATM gene in long-lived individuals and coronary artery disease patients." (PMID 28806901, 2017). "Earlier epidemiologic data indicate that the rate of ischemic heart disease-related mortality is significantly higher among heterozygous ATM carriers than that in the general population." (PMID 28806901, 2017). "Heterozygous patients for the ATM allele display an enhanced risk of death from ischemic heart disease in comparison with noncarriers." (PMID 36156462, 2023). "ATM mutation carriers were reported to have higher mortality rates compared with noncarriers due to the occurrence of ischemic heart disease and cancer." (PMID 36156462, 2023).
oesophageal cancer (11 papers, 2012 to 2025). "The mutation of ATM in humans and mice usually causes ALLs; some adult A-T patients also experience solid tumors including breast, gastric, or esophageal carcinomas." (PMID 35203601, 2022). "Six germline variants of ATM were coupled with somatic ATM mutations in prostate adenocarcinoma, rectum adenocarcinoma, stomach adenocarcinoma, esophageal carcinoma, prostate adenocarcinoma, and bladder urothelial carcinoma." (PMID 34771661, 2021). "The findings showed that AlPcS4Cl-PDT, treated oesophageal cancer cells, triggered DNA damage response signaling via DNA double-strand break and ATM pathways." (PMID 38347844, 2024). "This assay concurrently detects the expression of phosphorylated ATM, H2A.X and detection of DNA double-strand break (DSB) (co-expression of ATM/H2A.X cells) in the control and AlPcS4Cl -PDT treated oesophageal cancer cells." (PMID 38347844, 2024).
T-cell prolymphocytic leukemia (11 papers, 2004 to 2025). A slow-growing type of leukemia (blood cancer) in which too many lymphocytes are found in the bone marrow and/or blood. "This mutation produces near full-length detectable ATM protein that lacks protein kinase activity and was also found in T-cell prolymphocytic leukemia (T-PLL) patients." (PMID 34771661, 2021). "The pathogenesis of T-cell prolymphocytic leukemia involves recurrent genetic alterations, including TCL1A rearrangements and ATM mutations, which promote genomic instability." (PMID 41259500, 2025).
adenoma (10 papers, 2013 to 2025). A neoplasm arising from the epithelium. "In this case, we propose that the patient’s germline ATM mutation and tumour-specific ARID1A mutation contributed to adenoma formation and malignant transformation." (PMID 41146957, 2025). "The promoters of three genes (FHIT, MLH1 and ATM) were found to be hypermethylated in a significantly higher fraction of adenomas that recurred compared to non recurring lesions." (PMID 25091577, 2014). "The highest-rated gene when comparing carcinomas versus adenomas was ATM (padjusted = 2.0 × 10–4, BF = 10.17)." (PMID 23096130, 2013). "A study exploring the association between DNA repair gene SNPs and adenoma found that SNPs on the ataxia telangiectasia mutated (ATM) gene rs17503908 were negatively related to adenoma in non-smokers, compared to smokers." (PMID 37074453, 2023). "The study identified mutations in senescence-associated genes, namely, ATM, PIF1, TELO2, XAF1, and RBL1, in five of twenty subjects with multiple adenomas, indicating germline loss-of-function variants in genes that regulate senescence pathways with the development of serrated adenomas." (PMID 40699620, 2025). "In particular, we identified three genes (MLH1, ATM and FHIT) differentially methylated in adenomas that recurred during the five-year follow up." (PMID 25091577, 2014). "In particular, MLH1, ATM and FHIT gene promoters were found to be significantly hypermethylated in recurring adenomas." (PMID 25091577, 2014). "We also found that the promoter region of ATM is significantly methylated in the transition from adenoma to carcinoma; however, this does not correlate with expression of ATM." (PMID 23096130, 2013). "We then compared the mean methylation levels of gene promoters in R and NR patients, confirming that MLH1, ATM and FHIT were significantly differentially methylated in adenomas on the basis of the presence or not of lesion recurrence." (PMID 25091577, 2014).
Alzheimer disease (10 papers, 2014 to 2024). A progressive, neurodegenerative disease characterized by loss of function and death of nerve cells in several areas of the brain leading to loss of cognitive function such as memory and language. "Shen and his colleagues found that ATM signaling failure was associated with neuronal death in Alzheimer's disease (AD)." (PMID 33294447, 2020). "The combined evidence strongly points to a significant loss of ATM level during the progression of Alzheimer’s disease." (PMID 27022623, 2016). "We thus propose that the loss of ATM function is a key part of the mechanism of neuronal death found in Alzheimer’s disease." (PMID 27022623, 2016). "Based on these findings in mice with genetic ATM deficiency, we next tested mouse models of Alzheimer’s disease to determine whether our hypothesis for a reduction of ATM might be present." (PMID 27022623, 2016). "In 2023, in the frame of our experiments on Alzheimer’s disease (AD), we observed that the ataxia telangiectasia mutated protein (ATM) kinase protein, a DNA damage sensor, localizes around the nucleus of skin AD fibroblasts by forming a perinuclear crown of ATM." (PMID 39451221, 2024). "Therefore, we tested the hypothesis that a neuronal ATM deficiency might be involved in the neurodegeneration found in Alzheimer’s disease." (PMID 27022623, 2016). "They showed reduced ATM levels in lysates of human frontal cortex and cerebellum of Alzheimer’s disease (AD) subjects." (PMID 32858941, 2020). "Importantly, the data in the current manuscript suggests that even small reductions in neuronal ATM function are enough to induce the phenotypes akin to those observed in the frontal cortex of human Alzheimer's disease (AD) patients where mild ATM loss may be a contributing factor." (PMID 27022623, 2016). "Also, reductions in ATM signaling have been highlighted in the frontal cortex of patients with Alzheimer’s disease (AD), whereas increased ATM levels were reported in the cerebellum of AD patients." (PMID 37681912, 2023). "Previous studies have showed that the glutamine levels are lower in the brains of patients with Alzheimer's disease (AD), and the glutamine supplementation could reduce inflammation-induced neuronal cell cycle activation, tau phosphorylation, and ATM-activation in a mouse model of AD." (PMID 31119171, 2019). "We have also shown that, in Alzheimer’s disease, the fraction of hippocampal pyramidal neurons with nuclear HDAC4 increases significantly, suggesting a failure of ATM signaling." (PMID 24465754, 2014).
astrocytoma (10 papers, 2007 to 2026). "The ATM Ser49Cys variant was suggested from our previous familial melanoma and astrocytoma study as being a modifier of impact of a CDKN2A p14ARF variant, associating with an earlier age of onset." (PMID 38338943, 2024). "For astrocytoma, BRAF, ATM, CDKN2A, and EGFR mutations/amplifications were highly enriched in our cohort." (PMID 32373528, 2020). "A recent study reported that MST312 induces G2/M cell cycle arrest and acute ATM-pathway-dependent DNA damage in astrocytoma cells." (PMID 21827695, 2011). "Increased pH2AX, which has been found in our study and in astrocytoma, has been involved in cell cycle arrest as a result of ATM activation." (PMID 21827695, 2011). "Furthermore, polymorphisms in CHAF1A and XRCC1 are associated with the risk of astrocytoma, whereas SNPs in EME1, ATM, GLTSCR1, and XRCC4 are associated with susceptibility to non-astrocytoma subtypes." (PMID 27613841, 2016). "Based on our proposed three-hit hypothesis, D1853N in conjunction of IVS 38- 63T>A and IVS 38- 30 A>G within ATM gene, comprised the triangle of astrocytoma development in an Iranian proband affected with astrocytoma as well." (PMID 24312913, 2013). "Unlike astrocytoma cells that showed impairment of ATM phosphorylation and therefore were presumably unable to activate ΥH2AX, we found increased levels of phospho-ΥH2AX in GICs after FTH1 knockdown." (PMID 31491006, 2019).
colorectal tumors (10 papers, 2010 to 2025). "Furthermore, this patient carried an ATM p.F61Lfs*15 mutation, which has been found in few, mostly colorectal tumors (CosmicID: COSV53735143)." (PMID 39876058, 2025). "Additionally, we found a heterozygous nonsense mutation in APC and frameshift indels in known colorectal tumor suppressors; ATM, SOX9, RNF43, and ZFP36L2, of likely driver status." (PMID 32697969, 2020). "It will be important in future studies to study the anti-tumor effect of ATM inhibitor in autochthonous colorectal tumor model which is closer to the immune environment of human colorectal tumors." (PMID 39033176, 2024). "In colorectal tumors with an impaired MMR system, mutations of intronic mononucleotide repeats in ATM and MRE11 were found to result in aberrant splicing, followed by reduced expression of the wild-type protein." (PMID 24324828, 2013). "DNMT inhibitors, positively affecting the levels of ATM, increase radiosensitivity in human colorectal tumor cell lines." (PMID 21108789, 2010). "This is based upon the detection of basal pSer33-RPA32 levels, RAD51 foci, ATM, and RAD51C expression in formalin-fixed paraffin-embedded colorectal tumor samples or derived preclinical models." (PMID 39456536, 2024). "GSEA also showed enrichment of ATM/DDR-related genes in the myofibroblastic stroma of ovarian, esophageal, liver, and colorectal tumors, consistent with proteomic analysis of esophageal and breast CAF performed elsewhere." (PMID 36353752, 2022).